HNF1A (HNF1 homeobox A)
Diseases named in the same sentence as HNF1A in open-access papers (continued):
Sharing a sentence is not in itself a finding about the gene and the disease.
tumor (continued). "The molecular tumor subtype was defined by immunohistochemical staining for KRT81 and HNF1a as quasi-mesenchymal (QM) vs. non-quasi-mesenchymal (non-QM)." (PMID 32155990, 2020).
cancer (67 papers, 2006 to 2025). A tumor composed of atypical neoplastic, often pleomorphic cells that invade other tissues. "High-throughput analysis of cancer cell genomes has established that hotspot mutations in HNF4α and HNF1α occur in a variety of human cancers, including liver, renal, colorectal, and pancreatic carcinomas (ICGC Database)." (PMID 34771521, 2021). "GLUT1 was reported as a prognostic gene in CRC29, and our results suggest that HNF1A plays an important role in cancer glucose metabolism in association with HIF1A." (PMID 33990627, 2021). "Underlying factors that ectopically activates HNF1A in cancer cells represents an important event in aberrant transdifferentiation in ADM and in EMT." (PMID 32552862, 2020). "This provided further evidence that HNF1A function is not only relevant to Kdm6a‐regulated programs in the non‐tumoral pancreas, but also to Kdm6a‐deficient cancer." (PMID 32154941, 2020). "Since an exocrine-like subtype of PDAC has recently been identified and because HNF1A has been shown to be a novel cancer risk gene of PDAC32, it is likely that the HNFA/MIA2 secretory axis is active in PDACs." (PMID 25657029, 2015). "The fusion splices for eight of the 45 PCR validated fusions were not predicted to coincide with ensembl exon boundaries, including CMKLR1-HNF1A and CRADD-ERBB3 involving cancer associated HNF1A and ERBB3." (PMID 21625565, 2011). "Interestingly, a recent study provided direct evidence that HNF-1α is a transcriptional repressor of PPARγ in the liver steatosis-associated cancer models, highlighting a mechanism that seems to be conserved evolutionarily in both mice and humans." (PMID 41614817, 2025). "Likewise, the other two common variants associated with cancer in the discovery analysis, namely rs1882149 and rs7961178, are located in the intergenic region of the Hepatocyte Nuclear Factor-1alpha (HNF1A) gene." (PMID 33531528, 2021). "Additionally, the identification of HNF4α and HNF1α as mutated targets in cancer suggests that systematic searches through cancer cell genomes for somatic mutations will ultimately provide a full picture of the pathophysiology and therapeutic opportunities for underlying human oncogenesis." (PMID 34771521, 2021). "It is also possible that S100A2’s function as a transcriptional cofactor is more prominent in ccRCC due to the differential expression or activity of interacting proteins like HNF1A in this cancer type." (PMID 40011447, 2025). "Mechanistically, we demonstrate that S100A2 accelerates cancer progression through its interaction with the transcription factor HNF1A, leading to activating GLUT2 transcription." (PMID 40011447, 2025). "In recent years, there have been many reports on HNF1A-mediated regulation of drug resistance in cancer therapy." (PMID 38228910, 2024). "It was also reported that HNF1α suppresses the occurrence and progression of HCC by inhibiting cancer-associated PPARγ, Wnt, and NF-kB signaling." (PMID 38879600, 2024). "In parallel, the transcription factor activity related to pro-metastatic response (SMAD1,2,3 and HNF1a) and cancer cell maintenance (OCT4, and ATF1) was similarly increased at 4 h and remained pronounced through the 8 h time point following CM incubation." (PMID 38398186, 2024). "To delineate the transcriptional control of this module, we investigated associated TFs, highlighting the roles of prominent cancer‐associated TFs, such as CENPA, HNF1A, and E2F7." (PMID 39102671, 2024). "From the International Cancer Genome Consortium (ICGC) database of cancer genomes, we identified several HNF1A mutations located in the functional Pit-Oct-Unc (POU) domain." (PMID 35327967, 2022). "Our results suggest that in cases of high HNF1A expression or chemoresistant CRC after chemotherapy, inhibiting HNF1A can mitigate resistance to anti-cancer agents and augment chemotherapy." (PMID 33990627, 2021).
cancer (continued). "Further, exposure to anti-cancer agents increased HNF1A mRNA expression in primary cultured cells and suppression of HNF1A using miR1915 improved chemosensitivity." (PMID 33990627, 2021). "HNF1α directs the transcription of oncogenic cancer stemness genes and correlates with a reduced survival in patients." (PMID 32552862, 2020). "The expression levels of HNF1α in all cancers (found by using TCGA database through the UALCAN portal) revealed higher HNF1α expression in PDAC pancreata compared to normal pancreata." (PMID 33214606, 2020). "Today, it has been proved that HNF-1α shows protective behavior against cancer, while HNF-1β seems to promote tumorigenesis." (PMID 31685031, 2019). "They isolated cancer cells and tumor-associated fibroblasts (TAFs) from human HCC tissues and proved that HCC cells have blunted expression of HNF-1α, whereas forced re-expression of HNF-1α reduced the in vitro proliferation of HCC and TAF cells." (PMID 31685031, 2019). "These tumors contained few cancer stem cells, suggesting that HNF1A is important for maintaining the stem cell state." (PMID 30074477, 2018). "Moreover, the cancer-promoting effects of TRIM8 in HCC were abolished by the HNF1α-K197R mutant in vitro and in vivo." (PMID 38879600, 2024). "The role of HNF1A in cancer is controversial, based on anterior research." (PMID 34234870, 2021). "Ectopic expression of HNF1A in CK19+ cancer cells might indicate multistep tumorigenesis of cancer clones comprised of a HNF1A+ lineage that might lead to cancer subtypes." (PMID 32552862, 2020). "However, we observed that both PDAC cancer cells widely expressed HNF1A and MIA2 and some cancers even expressed them at a very high level." (PMID 25657029, 2015). "This evidence suggests that HNF1A could play a role in cancer development through regulation of immunity, inflammatory response, and protein folding, as well as cell growth and differentiation." (PMID 25793983, 2015). "We knocked down the HNF1A gene expression in two cancer cell lines using three siRNA sequences." (PMID 25793983, 2015). "However, it seems that HNF1A showed different functions in different cancers." (PMID 31810492, 2019). "While direct regulation of POU5F1/OCT4 and HNF1A was not explored in this study, it does support an association between these two transcription factors, not only in gastrointestinal cells, but other cancers as well." (PMID 30074477, 2018). "The role of HNF1α in the regulation of core versus outer arm fucosylation may be the molecular mechanism behind the reported association between common variants of HNF1α and inflammatory markers such as CRP as well as several diseases where inflammation plays a key pathogenic role such as cancer." (PMID 28657165, 2017). "Recurrent P/LP variants were identified in individuals diagnosed with cancer from distinct families, in the following cancer genes: BRCA1 (n = 3), LZTR1 (n = 3), HNF1A (n = 2), CHEK2 (n = 2), MITF (n = 2), and CHD4 (n = 2)." (PMID 37377903, 2023). "This study revealed that HNF1A is downstream of POU5F1 and high HNF1A expression in cancer tissue is an independent marker of poor prognosis, which is related to CRC recurrence and patient mortality." (PMID 33990627, 2021). "The majority of the DEGs, e.g., SOX11, TBX21, FAM3B, FGF5, HNF1A, MYB, and PLAC8 have been reported to function as promoters or biomarkers in various cancer types." (PMID 34440579, 2021).
cancer (continued). "In mouse tumors, HNF1A+; CK19+ cancer cells were present in tumoral tissue sections from both the vehicle-treated and the gemcitabine-treated KPC mice." (PMID 32552862, 2020). "Analysis of the HNF1A+; CK19+ cancer cells in local human specimen and in KPC mouse tumors revealed a consistent role of HNF1A expression in cancer progenitor cells." (PMID 32552862, 2020). "Over the period of three decades, notable HNF-1α data on HCC and related cancers perpetually drizzled over scientific horizon, but these efforts lack proper compilation." (PMID 31685031, 2019). "An oncogenic role for HNF1A in PDAC and other cancers has been supported by other studies as well." (PMID 40731412, 2025). "HNF1A specifically activates the transcription of the proto-oncogene SRC from an alternative promoter, giving rise to the long isoform c-SRC, whose transcripts are differentially present in several cancers, depending on the level of HNF1A." (PMID 38893242, 2024). "Notably, the RNA-Seq data obtained from The Cancer Genome Atlas (TCGA) database of cancer patients showed that the expression of HNF4A and HNF1A mRNA is significantly correlated in many cancer types." (PMID 35327967, 2022). "For cancer, identified targets include VEGFB, VEGFR2, MAP2, MMP14, HNF1A, TUSC5 and KLF12." (PMID 35356223, 2022). "Additionally, an IPA analysis of possible upstream regulators of the differentially expressed proteins yielded a mechanistic network regulated by HNF1A (TCF1) and CTNNB1, a well-known cancer regulatory hub important for the Wnt signaling pathway." (PMID 29515771, 2018). "Typically a marker of endodermal differentiation, HNF1A has not previously been reported as necessary for normal or cancer stem cells." (PMID 30074477, 2018). "HNF1A expression was barely detectable in MiaPaCa-2 cells and not detectable in the remaining carcinoma cell lines and HPDE." (PMID 25793983, 2015). "The expression of HNF1A was lower in cancer cell lines as compared to non-cancerous cell lines." (PMID 31685031, 2019). "As cooperation with oncogenic KRAS was observed in these cells, it is feasible that HNF1A provides additional oncogenic input, possibly by altering the differentiation state of KRAS-mutant, precancerous pancreatic cells or by expanding the resident stem cell/cancer stem cell population." (PMID 30074477, 2018). "miR-484 is a key factor in cancer and non-cancerous diseases, and its targets in cancer include VEGFB, VEGFR2, MAP2, MMP14, HNF1A, TUSC5, and KLF12." (PMID 36572856, 2022). "Many of these genes, including KEAP1, HNF1A, NFE2L2 and LRRK2, have implied roles in cancer but no strong mechanistic links to date (Discussion)." (PMID 30803482, 2019).
infection (14 papers, 2010 to 2024). The state of being infected such as from the introduction of a foreign agent such as serum, vaccine, antigenic substance or organism. "In contrast, HBV gene expression and replication were elevated in Huh7 cells with reduced endogenous HNF1α expression caused by the infection of the anti-HNF1α shRNA-expressing lentivirus." (PMID 28319127, 2017). "The overexpression of HCV NS5A during HCV J6/JFH1 (belonging to genotype 2a) infection leads to lysosome-dependent HNF-1α degradation." (PMID 39599533, 2024). "The overexpression of HCV NS5A promotes the binding of HNF-1α to HSC70, and HCV JFH1 infection also increases the binding of HNF-1α to HSC70." (PMID 39599533, 2024). "K20 and SI were induced following combined infection with Cdx2 and HNF1α whereas villin expression was reduced." (PMID 27875772, 2017). "Cell survival and apoptosis were determined 7 days post-infection with the HNF1α-expressing lentivirus at various MOI to establish its effect on cell viability." (PMID 24733486, 2014). "The infectivity of HNF1α-expressing lentivirus on Hep G2 cells was determined 7 days post-infection by flow cytometry to measure the rate of copGFP+ cells." (PMID 24733486, 2014). "In these cells, the levels of HNF1α and HNF4α were gradually decreasing after infection." (PMID 32793175, 2020). "We hypothesize that the role of HNF1α and its transcriptional co-factor HNF4α in the regulation of fucosylation is an essential part of mounting an acute phase response to infection in humans." (PMID 21203500, 2010). "Immunofluorescence analysis revealed that HCV J6/JFH1 infection promoted the colocalization of HCV NS5A and HNF-1α." (PMID 39599533, 2024). "By 5 days after infection, we observed GFP+ cells and a significant reduction in HNF1A mRNA as measured by quantitative PCR (qPCR)." (PMID 37943614, 2023). "HNF1α transduction of CYP3A4 activity was found to be time-dependent and peaked at 7 days post-infection, after which point, the activity declined." (PMID 24733486, 2014). "Subsequent infection with Cdx2 induced K20 and SI expression, while HNF1α did not." (PMID 27875772, 2017). "Moreover, HCV J6/JFH1 infection leads to HNF-1α degradation, which is inhibited by gene knockdown of LAMP2A and HSC70, and by ammonia chloride treatment, suggesting that HCV infection may activate CMA to degrade HNF-1α." (PMID 39599533, 2024).
cardiovascular disease (10 papers, 2017 to 2026). "The three HNF1A gene variants (rs1169288, rs2464196 and rs735396) were selected on the basis of several previous studies reporting the association of these SNPs with T2D and cardiovascular diseases which are related to MetS as being a component or a complication." (PMID 35109885, 2022). "In this light, studies on the development of cardiovascular diseases over time in the different HNF1A genotype carriers would be of interest." (PMID 37509590, 2023). "Prior studies have shown that HNF1A rs1169288 polymorphism is significantly associated with CRP concentration, cardiovascular diseases, and decreased in vitro transcriptional activity of downstream target gene promoters." (PMID 31915469, 2019). "These conditions may promote enhanced activation of sterol regulatory element-binding protein 2 (SREBP2) and hepatocyte nuclear factor-1 alpha (HNF1α) dependent transcription of PCSK9, thereby linking tobacco exposure to impaired lipid metabolism and increased cardiovascular disease risk." (PMID 41516208, 2025). "Consistent with other studies, there are 19 SNPs within a 43 Kb span on chr 12 encompassing the HNF1A gene, a hepatic transcription factor which has been repeatedly found to affect CRP expression, as well as C12orf43, variants of which have been linked to cardiovascular disease and CRP expression." (PMID 31622379, 2019). "Despite the pharmacologically controlled glycemia in HNF1A-MODY patients, still cardiovascular disorders and other endothelial dysfunction diseases, such as retinopathy, are quite common." (PMID 41749365, 2026).
metabolic disease (8 papers, 2015 to 2025). A congenital disorder (due to inherited enzyme abnormality) or acquired (due to failure of a metabolically important organ) disorder resulting from an abnormal metabolic process. "Therefore, loss of HNF-1α functionality can cause metabolic disorders such as hypercholesterolemia." (PMID 26413797, 2015). "We discovered that HNF4A is the central gene in the network of NASH connected to metabolic diseases and that it regulates HNF1A, an additional transcription regulator also involved in lipid metabolism." (PMID 29216278, 2017). "In our study, HNF4A is present in the network of NASH connected to metabolic diseases and regulates HNF1A, an additional transcription regulator also involved in lipid and amino acid metabolism." (PMID 29216278, 2017). "Aside from metabolic disorders, HNF-1α also regulates the expression of acute phase proteins, such as fibrinogen and interleukin 1 receptor, which are involved with inflammation." (PMID 26413797, 2015). "Although our participants were free of metabolic disorder diagnoses, a supposed gradation in insulin concentrations in the participants according to their different HNF1A genotypes could offer an explanation for the progression in antioxidant capacity among these participants." (PMID 40573148, 2025). "In general, long-term outcomes of lipid perturbations on metabolic diseases as well as on related morbidity and mortality in patients with HNF4A-MODY, GCK-MODY, HNF1A-MODY, and HNF1B-MODY require future investigations." (PMID 39504571, 2025). "Lastly, we extended our findings to diabetic patients and measured circulating miR-375 levels in human subjects with inactivating mutations in HNF1α (maturity-onset of the young, type 3 (MODY3)), T2D, T1D, and healthy subjects (no diagnosed metabolic disease (NDMD))." (PMID 26013143, 2015).
kidney disease (6 papers, 2017 to 2025). "HNF1A and HNF1B are two transcription factors that are closely associated with kidney disease, and both of these transcription factors showed decreased activity in proximal tubule cells with LOY." (PMID 38287344, 2024). "Some of these genes are known for rare Mendelian kidney disease where now a new common or less-frequent variant is implicated for affecting general kidney function (PKDH1 with new certainty, NPHS1 and HNF1A in novel loci), a phenomenon observed also in other contexts, like MC4R for obesity." (PMID 34272381, 2021).
retinopathy (6 papers, 2013 to 2026). "The frequency of retinopathy was low, and the presence of microalbuminuria was 0% in ABCC8‐MODY and KCNJ11‐MODY, while microalbuminuria ranged from 1.8% in HNF4A‐MODY and HNF1A‐MODY to 16.7% (1 out of 6 individuals) in KLF11‐MODY." (PMID 39511990, 2024).
liver (2 papers, 2019). "Thus, baicalin protects against estrogen-induced cholestatic liver injury, and the underlying mechanism involved is related to activation of the Sirt1/HNF-1α/FXR signaling pathway." (PMID 32116682, 2019). "Abundant clinical and rodent data have noted the downregulation of HNF-1α in parallel with liver malignancies." (PMID 31685031, 2019). "This subject presents a novel futuristic opportunity to harness HNF-1α as a target to understand and treat liver malignancies, possibly by impacting cell stemness." (PMID 31685031, 2019). "Abundant clinical and laboratory data concluded that downregulation of HNF-1α correlated with the progression in liver malignancies that persist with metabolic dysregulations." (PMID 31685031, 2019). "In summary, our results demonstrated that baicalin protected EIC rats against cholestatic liver injury by restoring hepatic BA homeostasis and modulating the inflammatory response through activating the Sirt1/HNF-1α/FXR signaling pathway." (PMID 32116682, 2019).
benign tumors (1 paper, 2011). "Whereas in benign tumors, we could think that TGFβ overexpression would induce apoptosis but HNF1α-mutated HCA do not show important necrosis and transcriptomic analysis did not reveal important changes in genes involved in apoptosis or cell cycle arrest." (PMID 21975049, 2011).
colonic polyps (1 paper, 2023). "Accordingly, we found that both the Hnf1aA98V/+ and Hnf1aA98V/A98V mice developed colonic polyps when fed a HFD, demonstrating that a loss of HNF1A function contributes to diet-related tumorigenesis." (PMID 37219942, 2023).
heart disease (1 paper, 2024). "In contrast, there is a slightly larger body of recent literature linking Hnf1a to inflammation and immune system response in diverse disease models, such as heart disease or steatohepatitis." (PMID 38825059, 2024).